SELENOP (selenoprotein P)
Diseases named in the same sentence as SELENOP in open-access papers (continued):
Sharing a sentence is not in itself a finding about the gene and the disease.
Sepsis (12 papers, 2014 to 2025). Sepsis is defined as life-threatening organ dysfunction caused by a dysregulated host response to infection. "The metabolism of selenium is disturbed during sepsis, leading to a reduction in serum selenium levels caused by the diminished synthesis of Selenoprotein P [SelP], the selenoprotein that plays a crucial role in selenium transport." (PMID 40867920, 2025). "Additionally, both capillary leakage and endothelial dysfunction caused by sepsis or ischemia–reperfusion injury leads to the additional loss of serum selenoproteins into the interstitium or selenoprotein P (SePP) binding to the endothelium." (PMID 35448461, 2022). "Selenoprotein P is the most prevalent selenoprotein in plasma and has been proposed to be the most important marker of Se deficiency in sepsis, which supports arguments against the role of GPx as an antioxidant in plasma in the absence of glutathione in this compartment." (PMID 24716537, 2014). "Due to altered hepatic Se metabolism, sepsis patients exhibit decreased plasma Se concentrations as synthesis of the protein that transports Se, selenoprotein P (SelenoP), decreases in the liver and therefore less Se is transported throughout the body." (PMID 34777335, 2021). "It has been demonstrated that SELENOP has endothelium-protecting activity in subjects with sepsis-related endothelium-dysfunction by binding to the endothelium, therefore depleting the plasma of SELENOP." (PMID 32131476, 2020). "It is related to the binding of selenoprotein-P to the endothelium in sepsis, to the protein extravasation at the early phase of sepsis, and to downregulation of selenoprotein-P liver synthesis." (PMID 31064391, 2019). "Low serum selenium or selenoprotein P (SePP) levels have been repetitively observed in severe sepsis, and both purified SePP and synthetic peptides corresponding to the His-rich motifs neutralized LPS." (PMID 29725935, 2018). "All of these adverse conditions coincide in severe sepsis, where AGs are applied under pro-inflammatory conditions, potentially contributing to a strong and health-relevant suppression of SELENOP biosynthesis and interruption of SELENOP-dependent Se-transport to target organs." (PMID 28663583, 2017). "In their investigation, Julian Hackler and colleagues explored the significance of selenium (Se) and copper (Cu) levels, as well as the biomarkers selenoprotein P (SELENOP) and ceruloplasmin (CP), in identifying early-onset sepsis (EOS) in neonates." (PMID 39655034, 2024).
colon carcinoma (10 papers, 2015 to 2023). "The downregulation of SELENOP, GPx1, and GPx3 is associated with tumorigenesis in colon cancer." (PMID 37895024, 2023). "Intestinal epithelial SELENOP knockdown increases the tumor load and genomic instability in cancer associated with the colitis model, suggesting its important role in the development of colon cancer." (PMID 37895024, 2023). "The down-regulation of GPx1, GPx3 and SELENOP is associated with the tumogenesis of colon cancer." (PMID 35624837, 2022). "Intestinal epithelial conditional deletion increases tumor load and genomic instability in the CAC model, suggesting an important role of SELENOP in colon cancer development." (PMID 35624837, 2022). "Moreover, SELENOP increased canonical WNT signaling activity in noncancer and colon cancer cell lines." (PMID 37166989, 2023). "SELENOP increases canonical WNT signaling activity in noncancer and colon cancer cell lines." (PMID 37166989, 2023).
Alzheimer disease (8 papers, 2016 to 2025). A progressive, neurodegenerative disease characterized by loss of function and death of nerve cells in several areas of the brain leading to loss of cognitive function such as memory and language. "Selenoprotein P co-localizes with amyloid-β plaques and neurofibrillary tangles in individuals with Alzheimer’s disease and inhibits aggregation and neurotoxicity of amyloid-β in mouse neuroblastoma cells." (PMID 26807844, 2016). "Selenoprotein P, a selenium-transporter protein, has been hypothesized to play a role in the etiology of neurodegenerative diseases such as amyotrophic lateral sclerosis (ALS) and Alzheimer’s dementia (AD)." (PMID 36077261, 2022). "Our subgroup analyses according to dementia types indicate that a role of selenoprotein P in predicting dementia conversion in individuals with MCI could be more pronounced for the forms not induced by Alzheimer’s dementia, such as frontotemporal dementia and Lewy bodies dementia." (PMID 37258587, 2023).
Hepatic steatosis (8 papers, 2014 to 2025). Steatosis is a term used to denote lipid accumulation within hepatocytes. "Therefore, overproduction of selenoprotein P in association with hepatic steatosis, by directly or indirectly lowering adiponectin levels, causes skeletal muscle IR." (PMID 24651470, 2014). "Specifically, MASLD-driven overproduction of fetuin-A and selenoprotein P impairs adipose tissue insulin signaling, creating a feedforward loop between hepatic steatosis and systemic IR." (PMID 40458180, 2025). "The observed correlation of reduced SELENOP levels with fatty liver disease has also been documented." (PMID 39001444, 2024). "In multiple regression analyses, alcohol intake was positively correlated with serum levels of both selenium and selenoprotein P independently of age, gender, liver enzymes, and fatty liver on ultrasonography." (PMID 33693023, 2021). "In multiple regression analyses, alcohol intake was positively correlated with serum levels of selenoprotein P independently of age, gender, liver enzymes, and fatty liver on ultrasonography in both men and women." (PMID 33693023, 2021). "Additionally, it has influenced key metabolic regulators, including gastrointestinal hormones (e.g., GLP-1, PYY) and hepatokines (e.g., fetuin-A, selenoprotein P), in individuals with hepatic steatosis." (PMID 41228524, 2025). "The liver communicates with pancreatic β-cells via hepatokines (e.g., fetuin-A, selenoprotein P) and inflammatory cytokines (e.g., IL-6, TNF-α) that are elevated in hepatic steatosis." (PMID 40691629, 2025).
Hyperglycemia (7 papers, 2018 to 2025). An increased concentration of glucose in the blood. "To date, there were no prospective studies that determine whether elevation of blood concentrations of SELENOP is linked to the future onset of hyperglycemia in humans." (PMID 30425271, 2018). "Chronic hyperglycemia induces systemic oxidative stress, potentially triggering a compensatory upregulation of SELENOP to mobilize selenium in response to redox challenges." (PMID 40416378, 2025). "Studies indicate that increased hepatic SELENOP mRNA expression correlates with hyperglycemia and reduced glucose tolerance in humans." (PMID 39469571, 2024). "SELENOP, which is also involved in antioxidative defense, has been rediscovered as a “hepatokine” capable of leading to IR and hyperglycemia." (PMID 35740085, 2022). "Conversely, the overproduction of SELENOP contributed to the development of IR and hyperglycemia in liver and skeletal muscle, whereas SELENOP knock-out mice fed a high-sucrose diet were protected against glucose intolerance and IR." (PMID 35740085, 2022). "The current study demonstrates that elevation of circulating hepatokine SELENOP is independently connected to future onset of hyperglycemia in healthy participants." (PMID 30425271, 2018). "The actions of short fragments of SELENOP on glucose metabolism are still unknown, but the current results suggest that increased levels of full length form of SELENOP are connected to future hyperglycemia in humans." (PMID 30425271, 2018). "Increased circulating levels of SELENOP might contribute to future hyperglycemia by inducing the other selenoproteins such as GPX1." (PMID 30425271, 2018). "However, the hypothesis that overproduction of SELENOP contributes to the pathogenesis in metabolic disorders is supported by the current findings that increased blood levels of SELENOP predict future onset of hyperglycemia in humans." (PMID 30425271, 2018). "The current data show that circulating levels of SELENOP, but not of selenium, were connected to the future onset of hyperglycemia in a general Japanese population." (PMID 30425271, 2018). "Finally, a recent study showed that the elevation of circulating SELENOP, but not of circulating Se, was connected to the future onset of hyperglycemia, probably due to the direct anti-oxidative enzyme activity of SELENOP independent of its Se transport capacity." (PMID 35740085, 2022).
neuroblastoma (7 papers, 2016 to 2025). Neuroblastoma (NB) is the most common solid, extracranial childhood tumor. "Two studies using recombinant expression of the histidine-rich domain of SELENOP (SelP-H) in neuroblastoma cells revealed the molecular mechanism by which SELENOP intervenes in Aβ aggregation and neurotoxicity through metal ion homeostasis." (PMID 40437610, 2025). "Therefore, additional studies on the inhibition of LRP8 in immunocompetent models are warranted to fully understand the therapeutic potential of targeting the LRP8/SELENOP axis for therapeutic benefit in neuroblastoma and other malignancies in particular the ones with amplified MYCN." (PMID 37435859, 2023). "Our data demonstrate that targeting SELENOP uptake via LRP8 is a valuable strategy to efficiently disrupt GPX4 maintenance and trigger ferroptosis in cultured MYCN‐amplified neuroblastoma cells." (PMID 37435859, 2023). "Their findings demonstrated that inhibiting the SELENOP/LRP8 axis represents a novel and selective strategy to trigger ferroptosis, thereby limiting the growth of highly aggressive and treatment-resistant MYCN-amplified neuroblastoma cells, confirming LRP8 as a promising therapeutic target." (PMID 40108662, 2025).
Autoimmunity (6 papers, 2017 to 2024). The occurrence of an immune reaction against the organism's own cells or tissues. "Firstly, our study describes the postulated occurrence of autoimmunity to SELENOP in female patients, with an expected association to higher patient age." (PMID 35636018, 2022). "The resulting Sec-poor SELENOP variants may induce ER stress, lose their capacity of transporting Se and might even become immunogenic, promoting autoimmunity." (PMID 28663583, 2017). "The role of selenium and SELENOP, combined with previous findings suggest strong candidacy of this protein as a biomarker of autoimmunity." (PMID 35330214, 2022). "The observed prevalence of 7.65% autoimmunity to SELENOP in the patients with primary invasive breast cancer is slightly higher than reported before from patients with autoimmune thyroid disease (6.6%), and healthy subjects (0.3%), respectively." (PMID 35636018, 2022). "In our study, the supplementation of high-dose selenite throughout the first week post-burn most likely prevented an even stronger decline in serum Se status and SELENOP biosynthesis, and therefore may have reduced the incidence of autoimmunity to SELENOP." (PMID 39176084, 2024). "Our data indicate that autoimmunity to SELENOP is a rare finding in healthy adult subjects." (PMID 34884891, 2021). "Although GPX3F activity was not significantly higher when compared with GPX3I, there was a significant increase in both Se and SELENOP levels after selenium supplementation, which may indirectly demonstrate the role of selenium in suppressing TGF-β-mediated autoimmunity." (PMID 35889825, 2022).
colitis (6 papers, 2015 to 2025). Inflammation of the colon. "In biopsies of colitis patients, SELENOP levels were low and associated inversely with disease severity." (PMID 40435558, 2025). "Selenoprotein P originates from the colonic epithelium and represents the source of antioxidant-mediated cancer protection associated with colitis." (PMID 37895024, 2023). "Selenoprotein P is a selenium-containing protein that contributes to antioxidant-mediated protection in colitis-associated cancer." (PMID 34663801, 2021).
Glucose intolerance (6 papers, 2013 to 2025). Glucose intolerance (GI) can be defined as dysglycemia that comprises both prediabetes and diabetes. "In conclusion, the current data reveal that elevation of circulating SELENOP is positively and independently associated with the future onset of glucose intolerance in a general population." (PMID 30425271, 2018). "The molecular mechanism by which aging increases SELENOP concentrations in the blood is currently unknown, but our study suggests that increased circulating SELENOP might contribute to aging-associated glucose intolerance in humans." (PMID 30425271, 2018). "In this context, C57BL/6J mice treated with intraperitoneal injections of purified human Selenoprotein P showed glucose intolerance and insulin resistance." (PMID 35204134, 2022). "The results of the study suggest that SELENOP impairs insulin signalling in the liver and skeletal muscle and induces glucose intolerance in vivo." (PMID 35204134, 2022). "Unchanged levels of SELENOP could be explained by the fact that severity of glucose intolerance was mild in the women with gestational diabetes." (PMID 30425271, 2018). "In addition, elevated plasma-SELENOP levels may predict the onset of glucose intolerance in healthy subjects." (PMID 35740085, 2022).
Hypertension (6 papers, 2015 to 2024). The presence of chronic increased pressure in the systemic arterial system. "SELENOP was linearly positively associated with hypertension in univariate (p = 0.023) and fully adjusted (p = 0.039) models." (PMID 37516012, 2023). "On the other hand, the positive association of SELENOP with hypertension was restricted to women." (PMID 37516012, 2023). "Surprisingly, however, there was a positive association of SELENOP with hypertension, which in turn was not seen in men, emphasizing the additional prognostic/diagnostic value of this Se status biomarker." (PMID 37516012, 2023). "In our study, patients with diagnosed hypertension (subgroup A) had statistically significantly lower selenoprotein P levels than patients without HT (subgroup B)." (PMID 37371917, 2023). "Fourth, we could not measure hepatokines such as fetuin-A, fibroblast growth factor 21, and selenoprotein P and levels of renin, angiotensin II and aldosterone which could explain the mechanism for an independent role of NAFLD in incident hypertension." (PMID 26618774, 2015).
adenoma (5 papers, 2018 to 2025). A neoplasm arising from the epithelium. "Since SELENOP upregulation correlated with the conventional adenoma-carcinoma sequence, we hypothesized that SELENOP deficiency would reduce stem cell–driven colorectal tumorigenesis." (PMID 37166989, 2023). "For SELENOP, there was a consistent inverse linear association in the adenoma and CRC groups, with a higher SELENOP concentration being associated with a lower HR for death." (PMID 40435558, 2025). "We observed increases in SELENOP expression throughout conventional adenoma to carcinoma progression." (PMID 37166989, 2023). "In human single-cell cRNA-Seq (scRNA-Seq) data sets, we discovered that SELENOP expression rose as normal colon stem cells transformed into adenomas that progressed into carcinomas." (PMID 37166989, 2023). "In human single-cell RNA-Seq (scRNA-Seq) data sets, we discovered progressive increases in SELENOP expression from stem to adenoma to carcinoma cells." (PMID 37166989, 2023). "However, the patients with CRC had significantly lower SELENOP levels compared to adenoma patients or controls." (PMID 40435558, 2025). "To test our hypothesis that SELENOP promotes intestinal tumorigenesis, we defined the effects of Selenop KO in an Apc-dependent adenoma mouse model." (PMID 37166989, 2023). "The prevalence of SELENOP-aAb differed between the groups and was 0.7 % in controls, and 5.4–5.5 % in patients with CRC or adenomas." (PMID 40435558, 2025). "GPX2 and TXNRD3 showed a higher expression and GPX3, SELENOP, SELENOS, and SEPHS2 exhibited a lower expression in the disease tissue from adenomas and both cancer groups (p-values from 0.023 to <0.001)." (PMID 30469315, 2018). "These included increasing down-regulation of GPX3, SELENOP, SELENOS, and SEPHS2 and up-regulation of GPX2, SELENOH, and TXNRD3, in groups of normal-matched tissues, adenomas, and adenomas with HGD." (PMID 30469315, 2018). "Mouse and cell culture studies indicated an important role of intestinal SELENOP expression for the progression of adenomas to carcinoma, e.g. by modulating WNT signaling through LDL receptor-related proteins, i.e., members of the same family as the established SELENOP-specific uptake receptors." (PMID 40435558, 2025).
Ataxia (5 papers, 2021 to 2024). Ataxia refers to impaired coordination of voluntary muscle movement. "Our results demonstrate that deletion of the SELENOP gene in dogs cause a defect in selenium transport associated with CNS atrophy and cerebellar ataxia (CACA)." (PMID 34339417, 2021). "Association of the SELENOP deletion with ataxia in 668 Belgian Shepherd dogs." (PMID 34339417, 2021). "It remains to be tested whether SELENOP-aAb are relevant for neurological disease, and whether SELENOP-aAb-positive thyroid patients are at particular risk for neurological sequelae, e.g., seizures, tremors, ataxia, or symptoms of Hashimoto encephalopathy." (PMID 34884891, 2021). "This study identified a deletion of SELENOP in Belgian Shepherd dogs with autosomal recessive CNS atrophy and cerebellar ataxia (CACA)." (PMID 34339417, 2021). "In the absence of regular and efficient SELENOP supply and uptake, severe neurological symptoms, including epileptic seizures, were observed in transgenic mice, and also recently in a dog model of impaired SELENOP expression, leading to brain atrophy and cerebellar ataxia." (PMID 34884891, 2021).
metabolic syndrome (5 papers, 2020 to 2025). A cluster of metabolic risk factors for CARDIOVASCULAR DISEASES and TYPE 2 DIABETES MELLITUS. "In a study of 200 people in Japan, serum LECT2 levels correlated positively with some clinical features of metabolic syndrome, namely body mass index, waist circumference, systolic blood pressure, serum selenoprotein P levels, and hemoglobin A1c blood levels." (PMID 38137613, 2023).